APOM (apolipoprotein M)
Diseases named in the same sentence as APOM in open-access papers (continued):
Sharing a sentence is not in itself a finding about the gene and the disease.
hyperlipidaemia (2 papers, 2016 to 2017). "Therefore, the specific effect of hyperlipidemia on serum apoM in patients with PNS should be studied to confirm whether the concentration of apoM is associated with hyperlipidemia or PNS." (PMID 28877724, 2017). "The serum apoM concentrations were lower in the PNS with hyperlipidemia group (25.1 ± 16.31 mg/L) than in the hyperlipidemia group (61.1 ± 23.21 mg/L; P = 0.001)." (PMID 28877724, 2017). "The concentration of apoM in patients with hyperlipidemia was higher than that in healthy controls, and apoM concentrations in PNS patients were lower than in healthy controls." (PMID 28877724, 2017). "Serum apoM levels in patients with hyperlipidemia were 61.1 ± 23.21 mg/L, i.e., much higher than those in the control group (31.6 ± 18.92 mg/L; P = 0.004)." (PMID 28877724, 2017). "The aim of this study was to measure the apoM levels in patients with hyperlipidemia, patients with PNS and hyperlipidemia, and patients with PNS but without hyperlipidemia by an enzyme-linked immunosorbent assay (ELISA)." (PMID 28877724, 2017). "The serum apoM concentration in patients with hyperlipidemia was found to be higher than that in healthy controls." (PMID 28877724, 2017). "Therefore, we hypothesized that the level of apoM may be associated with hyperlipidemia." (PMID 28877724, 2017). "The average serum apoM concentrations were higher in the hyperlipidemia group (61.1 ± 23.2 mg/L, P = 0.004) than in the healthy controls (31.6 ± 18.92 mg/L)." (PMID 28877724, 2017). "Hyperlipidemia is often associated with a decrease in serum HDL-C with elevated THOL and LDL-C, which is associated with apoM." (PMID 28877724, 2017). "This situation suggests that apoM in the VLDL/LDL pool is replenished from the HDL pool in hyperlipidemia patients with high serum concentrations of VLDL/LDL." (PMID 28877724, 2017). "Our study assessed the serum apoM levels in patients with hyperlipidemia and revealed that patients with hyperlipidemia had significantly higher apoM levels than healthy controls did." (PMID 28877724, 2017). "Our study mainly revealed that plasma apoM concentrations in patients with hyperlipidaemia were higher than those in healthy controls." (PMID 27633510, 2016). "ApoM was also positively correlated with apoB in the T2DM with hyperlipidaemia group (r = 0.220, P <0.05) and healthy controls (r = 0.351, P <0.001)." (PMID 27633510, 2016). "Significantly high plasma apoM levels are detected in hyperlipidaemia mice with a defective LDL receptor." (PMID 27633510, 2016). "The average plasma apoM concentrations were 18 % higher in the hyperlipidaemia group (26.63 ± 10.35 ng/μL) than in the healthy controls (22.61 ± 10.81 ng/μL, P <0.01)." (PMID 27633510, 2016). "Hyperlipidaemia is often accompanied with complex dyslipidaemia, such as increased LDL-C and VLDL-C levels and low HDL-C levels, which are associated with plasma apoM." (PMID 27633510, 2016). "The plasma apoM concentrations were lower in the T2DM with hyperlipidaemia group (19.83 ± 7.41 ng/μL) compared with those in the hyperlipidaemia group (26.47 ± 10.18 ng/μL, P <0.001)." (PMID 27633510, 2016). "Hyperlipidaemia often displays reduced plasma HDL-C and increased TC and LDL-C, which was associated with apoM." (PMID 27633510, 2016). "This study also aimed to determine the effects of hyperlipidaemia on plasma apoM levels in patients with T2DM." (PMID 27633510, 2016). "The plasma apoM concentration was negatively correlated with CYS-C in patients with hyperlipidaemia alone (r = −0.250, P <0.05)." (PMID 27633510, 2016). "This study determined the plasma apoM levels in patients with hyperlipidaemia and found that hyperlipidaemia patients have marked apoM levels than healthy controls." (PMID 27633510, 2016). "This study aimed to examine the apoM levels in patients with hyperlipidaemia, patients with T2DM and hyperlipidaemia, and patients with T2DM but without hyperlipidaemia through enzyme-linked immunosorbent assay (ELISA)." (PMID 27633510, 2016).
hyperlipidaemia (continued). "The plasma apoM concentrations were on average 18 % higher in hyperlipidaemia patients (26.63 ± 10.35 ng/μL) compared with healthy controls (22.61 ± 10.81 ng/μL; P <0.01)." (PMID 27633510, 2016). "In conclusion, plasma apoM concentrations were higher in patients with hyperlipidaemia than in healthy subjects." (PMID 27633510, 2016). "This research aims to examine the changes in apoM levels in patients with hyperlipidaemia and to determine the effects of hyperlipidaemia on plasma apoM levels in patients with T2DM." (PMID 27633510, 2016). "Increased plasma triglyceride (TG) levels and significantly high plasma apoM levels are detected in hyperlipidaemia mice with defective low-density lipoprotein (LDL) receptor." (PMID 27633510, 2016). "This condition leads to the VLDL/LDL pool of apoM that is replenished from the HDL in hyperlipidaemia patients with marked plasma VLDL/LDL levels." (PMID 27633510, 2016). "Serum apoM concentrations are higher in patients with hyperlipidemia than in healthy controls." (PMID 28877724, 2017). "However, few studies have shown how apoM is expressed in primary nephrotic syndrome (PNS), which is often accompanied with hyperlipidemia, and the underlying mechanism is poorly understood." (PMID 28877724, 2017). "The possible explanation for this result and the relation between hyperlipidemia and serum apoM levels may be that apoM can be rapidly exchanged between VLDL-C/LDL-C and HDL-C particles in vivo." (PMID 28877724, 2017). "Significantly elevated serum apoM levels are detected in patients with hyperlipidemia." (PMID 28877724, 2017). "Hyperlipidaemia was an independent promoting factor of plasma apoM levels." (PMID 27633510, 2016). "Plasma apoM concentrations are higher in patients with hyperlipidaemia than in healthy controls." (PMID 27633510, 2016). "Moreover, hyperlipidaemia was an independently promoting factor for plasma apoM." (PMID 27633510, 2016). "By contrast, low plasma apoM levels are observed in patients with T2DM, which is often accompanied with hyperlipidaemia." (PMID 27633510, 2016). "Therefore, low plasma apoM levels in T2DM patients were not caused by hyperlipidaemia." (PMID 27633510, 2016). "Among the renal variables, a negative correlation was detected between proteinuria and apoM in the PNS with hyperlipidemia group and PNS without hyperlipidemia group (r = −0.269, P = 0.036, and r = −0.414, P = 0.028, respectively)." (PMID 28877724, 2017). "The serum apoM concentration in the PNS without hyperlipidemia group also positively correlated with HDL-C, LDL-C, apoA1, and apoB (r = 0.458, P = 0.003; r = 0.423, P = 0.017; r = 0.254, P = 0.022; and r = 0.427, P = 0.036, respectively)." (PMID 28877724, 2017). "The serum apoM concentrations were determined in patients with hyperlipidemia, PNS without hyperlipidemia, PNS with hyperlipidemia and healthy controls." (PMID 28877724, 2017). "Similar to apoA-I (1.29 ± 0.33 g/L vs. 1.28 ± 0.31 g/L, P >0.05), the plasma apoM concentrations in the T2DM with hyperlipidaemia group did not significantly differ from those in the T2DM without hyperlipidaemia group (P >0.05)." (PMID 27633510, 2016). "Meanwhile, T2DM itself (β = −3.09, P = 0.005) was the independently negative factor for apoM, whereas hyperlipidaemia (β = 3.43, P = 0.001) was the positive factor." (PMID 27633510, 2016). "This study confirmed that the plasma apoM levels were reduced in T2DM patients with or without hyperlipidaemia than those in healthy controls." (PMID 27633510, 2016). "Thus, we can theorize that low serum apoM concentrations in PNS patients were not triggered by hyperlipidemia." (PMID 28877724, 2017). "Besides that, both the plasma apoA-I and apoM levels were not statistically different between the T2DM without hyperlipidaemia groups and T2DM with hyperlipidaemia groups." (PMID 27633510, 2016).
hyperlipidaemia (continued). "However, apoM was positively correlated with CYS-C in the T2DM with hyperlipidaemia group (r = 0.250, P <0.05) but was not correlated with CYS-C in the other two groups." (PMID 27633510, 2016). "A negative correlation was detected between proteinuria and apoM, and a positive correlation was observed between proteinuria and THOL in the PNS with hyperlipidemia group." (PMID 28877724, 2017). "The serum apoM concentrations were lower in the PNS with hyperlipidemia group (25.1 ± 16.31 mg/L, P = 0.007) and in the PNS without hyperlipidemia group (21.00 ± 17.62 mg/L, P = 0.003) than in the healthy controls." (PMID 28877724, 2017). "The plasma apoM concentrations were determined in patients with hyperlipidaemia (n = 79), T2DM without hyperlipidaemia (n = 125), T2DM with hyperlipidaemia (n = 98), and healthy controls (n = 105)." (PMID 27633510, 2016). "The plasma apoM concentrations were lower in the T2DM without hyperlipidaemia group (18.54 ± 10.33 ng/μL, P <0.01) and the T2DM with hyperlipidaemia group (19.83 ± 7.41 ng/μL, P <0.05) than in the healthy controls." (PMID 27633510, 2016). "However, the serum apoM concentrations were lower in the PNS without hyperlipidemia group (21.0 ± 17.62 mg/L,P = 0.003) and PNS with hyperlipidemia group (25.1 ± 16.31 mg/L,P = 0.007) than in the healthy control group (31.6 ± 18.92 mg/L)." (PMID 28877724, 2017). "No statistical difference was observed in plasma apoM concentrations between the T2DM with hyperlipidaemia group (19.83 ± 7.41 ng/μL) and T2DM without hyperlipidaemia group (18.54 ± 10.33 ng/μL, P >0.05) similar to apoA-I (1.29 ± 0.33 g/L vs. 1.28 ± 0.31 g/L, P >0.05)." (PMID 27633510, 2016).
IgA nephropathy (2 papers, 2021 to 2025). "Animal studies have shown that overexpression of ApoM via adenoviral gene transfer of ApoM in hyper-IgA mice suppressed proteinuria and ameliorated the phenotypes of IgA nephropathy." (PMID 40579063, 2025). "In the mouse IgA nephropathy model, glomerular mesangial cell proliferation and matrix expansion was suppressed by apoM, an effect that was mediated by ApoM-bounded S1P." (PMID 34360965, 2021).
kidney injury (2 papers, 2014 to 2024). Trauma to the kidney. "Also, within this compartment is ApoM, which has been previously identified to in soluble urine and associated with kidney injury." (PMID 25593928, 2014).
lipid metabolic disorders (2 papers, 2017). "In the current study, a positive correlation between serum ApoM and ApoA5 and HDL was observed, indicating that OSAHS might be involved in lipid metabolism disorder by regulating ApoM and ApoA5 on HDL." (PMID 27206623, 2017). "ApoM can regulate the formation of pre-β-HDL and the reverse cholesterol transport and thus plays an important role in the metabolism of lipids and lipoproteins, meaning that it can affect the development of lipid metabolism disorders." (PMID 28877724, 2017).
liver cirrhosis (2 papers, 2008 to 2021). "The expression of ApoM in cancer tissues and adjacent tissues is related to age (<50, P=0.010), gender (male, P=0.012), tumor size (P=0.020), necrosis (P=0.024) and liver cirrhosis (P=0.028), factors related to poor differentiation (P=0.0010)." (PMID 34149930, 2021).
lymph node metastasis (2 papers, 2010 to 2021). "Whether increased apoM expression in the patients with lymph node metastasis being related to patients' prognosis and the physiopathological importance of apoM expression in colorectal tissues need further investigation." (PMID 20846402, 2010).
polyp (2 papers, 2010 to 2020). A usually exophytic mass attached to the underlying tissue by a broad base or a thin stalk. "APOM protein level in cancer tissues was lower than that in paracarcinomatous (P = 0.0003) and polyp tissues (P < 0.0001)." (PMID 33173129, 2020). "In the present study, we therefore examined apoM expression in human colorectal tissues including cancer tissues, cancer adjacent normal tissues, polyp tissues and normal mucosa as well as inflammatory mucosa." (PMID 20846402, 2010). "In the present study, we examined apoM expression in normal mucosa, inflammatory mucosa, polyp and cancer tissues, which shows clearly that these tissues do express apoM, although apoM expression in the cancer tissues were significantly inhibited." (PMID 20846402, 2010). "However, apoM protein mass were significantly lower in the cancer tissues than its matched adjacent normal tissues, polyp tissues, normal mucosa and inflammatory mucosa." (PMID 20846402, 2010).
schizophrenia (2 papers, 2022 to 2023). A major psychotic disorder characterized by abnormalities in the perception or expression of reality. "Lipid-binding proteins ApoB, ApoD, ApoF, and ApoM were reduced in patients with schizophrenia, whereas ApoE was increased." (PMID 34741130, 2022).
viral infection (2 papers, 2011 to 2023). "In addition, dysregulated expression of APOM was reported to be associated with virus infection." (PMID 36859478, 2023). "A rise in the ApoM protein expression in response to viral infection poses a potential query that how this would affect the contributory viral agent." (PMID 21875437, 2011). "We found that ApoM levels rise during the viral infection and that over expression of ApoM suppresses HBV replication." (PMID 21875437, 2011).
autoimmune disease (1 paper, 2019). A disorder resulting from loss of function or tissue destruction of an organ or multiple organs, arising from humoral or cellular immune responses of the individual to their own tissue constituents. "Due to the vital role of apoM in autoimmune disease, it is essential to understand the role of apoM concerning autoimmune diseases." (PMID 31885732, 2019). "Several studies have been reported that apoM was reported in metabolic diseases, autoimmune diseases, and inflammatory diseases." (PMID 31885732, 2019).
Autoimmunity (1 paper, 2024). The occurrence of an immune reaction against the organism's own cells or tissues. "However, APOM’s role extends beyond metabolic and cardiovascular disorders, encompassing contributions to autoimmunity and inflammation." (PMID 38482005, 2024).
brain inflammation (1 paper, 2017). "Several reports identified a link between the apoM/S1P system and liver fibrosis as well as brain inflammation." (PMID 28749426, 2017).
cardiac arrest (1 paper, 2022). Cessation of breathing and/or cardiac function. "The effect of long-term cold exposure on plasma apoM and S1P was explored either by maintaining the core temperature at 36 ̊C or reducing it further to 33 ̊C in patients submitted after cardiac arrest." (PMID 36335116, 2022).
chronic hepatitis B (1 paper, 2016). "Levels of apolipoprotein M (apoM), a component of high-density lipoprotein (HDL), are known to be significantly elevated in patients with chronic hepatitis B (CHB)." (PMID 27927202, 2016).
Cognitive impairment (1 paper, 2022). Abnormal cognition is characterized by deficits in thinking, reasoning, or remembering. "Subsequently, the correlations between plasma ApoM and its derived indicators with clinical characteristics (i.e., cognitive impairment and ADL) and representative blood biomarkers (i.e., p-tau217 and NfL) of AD were analyzed, respectively." (PMID 35370599, 2022).
Cyanosis (1 paper, 2025). Bluish discoloration of the skin and mucosa due to poor circulation or inadequate oxygenation of arterial or capillary blood. "Patients with cyanosis are characterized by higher S1P serum levels (p = 0.04), lower ApoM (p = 0.04), and HDL concentrations (p = 0.02)." (PMID 40357437, 2025).
diabetic retinopathy (1 paper, 2026). "Our exploratory findings suggest a significant positive association between plasma apoM levels and diabetic retinopathy in patients with T2DM." (PMID 42051463, 2026). "Patients with diabetic retinopathy exhibited greater median plasma apoM levels than those without diabetic retinopathy (26.05 [21.09-30.37] mg/L vs. 21.47 [18.00-26.38] mg/L; p < 0.001)." (PMID 42051463, 2026).
experimental autoimmune encephalomyelitis (1 paper, 2017). An autoimmune demyelinating disease of the central nervous system that is produced experimentally in animals by the injection of homogenized brain or spinal cord in Freund's adjuvant. "A study recently has reported that APOM−/− mice developed more severe experimental autoimmune encephalomyelitis (EAE), characterized by increased lymphocytes in the central nervous system and breakdown of the blood-brain barrier." (PMID 28476116, 2017).
familial chylomicronemia syndrome (1 paper, 2017). A rare autosomal recessive disease characterized by the buildup in the blood of fat particles called chylomicrons (chylomicronemia), severe hypertriglyceridemia, and the risk of recurrent and potentially fatal pancreatitis and other complications. "Remarkably, this was associated with ∼50% decreases in both apoC-II and apoE, and modest increases in apoA-I, apoA-II, and apoM, whereas levels of apoB-100 did not change, except in the 3 subjects with familial chylomicronemia syndrome (FCS) (IONIS1), who experienced a marked decrease in TGs." (PMID 28209220, 2017).
fibrosis (1 paper, 2017). the formation of excess fibrous connective tissue in an organ or tissue in a reparative or reactive process. "The review will provide novel insights on apoM and S1P, and its role in hepatic fibrosis, neuroinflammation and BBB integrity." (PMID 28749426, 2017).
glomerulonephritis (1 paper, 2019). A renal disorder characterized by damage in the glomeruli. "Lower apoM levels were most pronounced in patients with rash and glomerulonephritis, the latter connected to central pathogenetic pathways in SLE together with presence of anti-dsDNA antibodies where lower levels of apoM were also seen." (PMID 31046824, 2019).
hepatitis B (1 paper, 2016). "Previous study showed that serum leptin was elevated in patients with hepatitis B patients, and apoM expression was lower in leptin deficient ob/ob mice." (PMID 27927202, 2016). "Since apoM functions as an anti-inflammatory and immune-modulatory factor, these results suggest that HBeAg may play a role in apoM-related lipid metabolism and anti-inflammatory functions in hepatitis B patients." (PMID 27927202, 2016).
lentivirus infection (1 paper, 2021). Virus diseases caused by the Lentivirus genus. "Here, lentivirus infection technology was used to overexpress ApoM in Caco-2 cells." (PMID 33564284, 2021).
leukopenia (1 paper, 2019). "ApoM levels were particularly low in patients with active disease from the kidney and skin and in patients with leukopenia or positive anti-dsDNA antibody test (p < 0.05)." (PMID 31046824, 2019). "Furthermore, patients with the SLEDAI-2 K item leukopenia, or presence of anti-dsDNA antibodies at the time point of blood sampling, had decreased apoM levels compared to patients with normal leukocyte count, or absence of anti-dsDNA antibodies (p < 0.01)." (PMID 31046824, 2019).
lung squamous cell carcinoma (1 paper, 2024). "Five of the ten target drug genes are detected in lung squamous cell carcinoma tissues, whereas the expression of CCNA2, APOM, C4A, PKD2L1, and CYP21A2 was not very significant." (PMID 39175755, 2024).
malignant melanoma (1 paper, 2024). "Similarly decreases of several apolipoproteins (APOB, APOE, APOM) in nonresponding patients have also been reported as prognostic markers for malignant melanoma." (PMID 38777088, 2024).
non-alcoholic fatty liver disease (1 paper, 2022). "Plasma ApoA-I exhibits a linear inverse correlation with BMI, while ApoM is also reduced in obese individuals and is inversely associated with non-alcoholic fatty liver disease (NAFLD), another comorbidity associated with obesity and an emerging risk factor for HF, in particular HFpEF." (PMID 35350538, 2022).
ovarian carcinoma (1 paper, 2023). A malignant neoplasm originating from the surface ovarian epithelium. "Although APOM is not yet confirmed to be increased or decreased in breast, cervical, and ovarian cancers, some mechanisms explain the plausible inhibition of the tumor growth through APOM." (PMID 38067270, 2023).